BRCA2 (BRCA2 DNA repair associated)
Diseases named in the same sentence as BRCA2 in open-access papers (continued):
Sharing a sentence is not in itself a finding about the gene and the disease.
ovarian carcinoma (continued). "Pathogenic coding variants in BRCA1, BRCA2 and PALB2 confer hereditary breast/ovarian cancer risk, yet these regions comprise less than 10% of the genomic footprint of these genes, leaving most sequence unexplored." (PMID 41935071, 2026). "We meta-analyzed >22 million variants for 398,238 women from the Ovarian Cancer Association Consortium (OCAC), UK Biobank (UKBB) and Consortium of Investigators of Modifiers of BRCA1/BRCA2 (CIMBA) to identify novel HGSOC susceptibility loci." (PMID 41266372, 2025). "Defects in the DNA repair pathways, such as mutations in BRCA1 and BRCA2, can enhance the PARP1 activity in breast and ovarian cancers." (PMID 41219748, 2025). "Several studies in the literature have demonstrated the potential chemo-preventive effect of oral contraceptives in reducing ovarian cancer risk among BRCA1 and BRCA2 mutation carriers." (PMID 41463165, 2025). "Germline and somatic mutations affecting HRR genes are relatively commonplace, affecting approximately one-third of ovarian carcinoma patients, with BRCA1 and BRCA2 mutations being the most prevalent." (PMID 40166687, 2025). "In ovarian cancer, pathogenic variants in BRCA1, BRCA2, RAD51C, RAD51D, and PALB2 predict PARP inhibitor efficacy, but this has not been established for other HRR-related genes." (PMID 40069561, 2025). "Some studies even showcase successful overcoming of resistance to the PARP inhibitor olaparib in BRCA2-mutant ovarian cancer, by targeted inhibition of ATR/Chk1." (PMID 40422251, 2025). "The PALB2 gene is often tested in individuals with a family history of breast or ovarian cancer, especially those with a known BRCA1 or BRCA2 mutation." (PMID 39996890, 2025). "Prior studies have elucidated key genes in the homologous recombination pathway, including BRCA1, BRCA2, RAD51, and PALB2, that commonly have pathogenic germline variants and/or somatic mutations in breast and ovarian cancers." (PMID 40327608, 2025). "Further recontact regarding risk-reducing bilateral salpingo-oophorectomy (RRBSO) should occur at different ages depending on gene-specific ovarian cancer risk: 35–40 years (BRCA1) and 40–45 years (BRCA2)." (PMID 41159931, 2025). "PARP inhibitors have been used with great clinical success in ovarian cancer associated with mutations in the BRCA1 and BRCA2 genes." (PMID 41375669, 2025). "Truncating variants in BRCA1, BRCA2, BRIP1 and RAD51D represent high‐risk variants for breast or ovarian cancer." (PMID 39440754, 2025). "Materials and methods: Patients with advanced stage III-IV epithelial ovarian cancer who had deleterious BRCA1 or BRCA2 were analyzed." (PMID 40075604, 2025). "Other studies have also reported a significantly reduced risk of developing ovarian cancer among BRCA1 and BRCA2 mutation carriers who had used combined oral contraceptives." (PMID 39863726, 2025). "Breast and ovarian cancers with mutations in the BRCA1 and BRCA2 genes are especially sensitive to PARP inhibitors." (PMID 40647506, 2025). "Models like BRCAPRO and BOADICEA are specifically tailored for individuals with a family history of breast and ovarian cancers, providing valuable insights into genetic mutations, including BRCA1 and BRCA2, as primary risk factors." (PMID 40599862, 2025). "A family history of breast or ovarian cancer is an important risk factor for ovarian cancer, with known genetic predispositions (primarily germline mutations in BRCA1 or BRCA2) accounting for 10%–15% of cases." (PMID 41169433, 2025). "BRCA1 alterations were particularly common in ovarian cancer (13.8%), while BRCA2 was prevalent in prostate cancer (8.3%)." (PMID 40420266, 2025). "Talazoparib was evaluated in phase I trials in patients with one of the following cancers: triple-negative breast cancer, ovarian cancer, prostate cancer, pancreatic cancer, and identified germline mutations of BRCA1 and BRCA2." (PMID 41155399, 2025).
ovarian carcinoma (continued). "In cases of ovarian cancer complications, even BRCA2 exhibit sufficiently high odds ratio of 3.06, but BRCA1 stood out with an odds ratio of 19.33, indicating a notably high probability." (PMID 40323562, 2025). "We have also observed a higher incidence of BRCA2 mutations in the CBI-high cohort, which confirmed the significant impact of BRCA mutation detection in the treatment of ovarian cancer." (PMID 40424327, 2025). "Regarding ovarian cancer, the risk associated with the presence of a BRCA pathogenetic variant gene in the case of BRCA1 and BRCA2 is 44% (95% CI = 36% to 53%) and 17% (95% CI = 11% to 25%), respectively." (PMID 41092066, 2025). "Oncology research on BRCA1 and BRCA2 mutations and their association with PARP inhibitors is still very active, especially in cases of breast and ovarian cancer." (PMID 40141415, 2025). "The risk of developing ovarian cancer for BRCA1 mutation carriers is about 44%, and for BRCA2 mutation carriers, it is about 17%." (PMID 40429755, 2025). "In ovarian cancer, BRCA1-mut cancer genes such as AIF1, CD8A, and BST1 showed detrimental prognosis, while in BRCA2-mut ovarian cancer, SEC61A2 and IGFBP3 were associated with shorter survival." (PMID 40647506, 2025). "Our study identified 19/728 carriers (2.6%) of pathogenic HDR gene variants, including 15 truncating variants, of which 4 were in BRCA1 or BRCA2 (0.5%) and 4 were in BRIP1 or RAD51D, two other genes associated with high ovarian cancer risk." (PMID 39440754, 2025). "For BRCA2-mut, only two and nine genes had surface expression and were upregulated in breast and ovarian cancers, respectively." (PMID 40647506, 2025). "Two ovarian cancer susceptibility genes have been located: BRCA1 and BRCA2, whose mutations are inherited in an autosomal dominant manner." (PMID 40429755, 2025). "Hereditary breast and ovarian cancer (HBOC) syndrome accounts for 5–10% of all breast and ovarian cancers, with BRCA1 and BRCA2 pathogenic variants being the most common genetic alterations." (PMID 41301857, 2025). "One of the most common genetic risk factors for ovarian cancer includes germline mutations in Breast Cancer gene 1 and 2 (BRCA1 and BRCA2, or BRCA1/2)." (PMID 41471359, 2025). "Conversely, two CNVs were identified in BRCA2, including a recurrent large deletion of exons 1 to 14 detected in five unrelated patients with breast or ovarian cancer." (PMID 40065011, 2025). "In our study, 20% (113/555) of the breast and ovarian cancer cases were identified as carriers of PVs in associated genes, with major contributions from BRCA1 and BRCA2 genes (12% and 17%, respectively)." (PMID 40065011, 2025). "It lies in the BRCA2 Ovarian Cancer Cluster Region (OCCR) and has been associated with Fanconi anemia in newborns bearing biallelic BRCA2 PVs." (PMID 40563557, 2025). "The predisposition to breast and ovarian cancer is caused by high-penetrance genes, such as BRCA1 and BRCA2, which are associated with a high risk of developing the disease." (PMID 40429755, 2025). "For instance, mutations in the BRCA1 and BRCA2 genes are strongly associated with an increased risk of breast and ovarian cancers, and genetic testing for BRCA1 and BRCA2 mutations help identify individuals at high risk." (PMID 40831536, 2025). "Inhibitors of poly(ADP-ribose) polymerase (PARP) have transformed the treatment of patients with BRCA-mutant breast and ovarian cancers, which typically develop in a background of germline mutations in BRCA1 or BRCA2." (PMID 40460119, 2025).
ovarian carcinoma (continued). "BRCA2, a known tumor suppressor gene for breast and ovarian cancers, also plays a role in immune response." (PMID 39796280, 2025). "In the prospective ovarian cancer cohort, pathogenic/likely pathogenic BRCA1/2 variants were detected in 24.19% of cases, with BRCA1 alterations more frequent than BRCA2." (PMID 41465396, 2025). "Breast and ovarian cancers are significant global health challenges, with inherited variations in breast cancer gene 1 (BRCA1) and breast cancer gene 2 (BRCA2) substantially increasing the risk, aggressiveness, and early onset of these diseases." (PMID 40071159, 2025). "SNRPB was found to be upregulated in ovarian cancer cells, promoted tumor growth, supported canonical BRCA2 splicing, and suppressed aberrant exon 3 skipping, thereby affecting the response to cisplatin." (PMID 40724944, 2025). "BRCA1/2-associated breast and ovarian carcinomas are often regarded as a single entity, assuming that BRCA1 and BRCA2 genes are almost equivalent with regard to their clinical significance." (PMID 40547808, 2025). "The small group of patients who were diagnosed with both breast and ovarian cancer had germline P/LP variants in BRCA1 (25%), BRCA2 (50%), and POLD1 (25%)." (PMID 40710012, 2025). "In a meta-analysis, cumulative risk of ovarian cancer among BRCA1 and BRCA2 mutation carriers was 39% and 11% respectively, by 70 years of age." (PMID 40894326, 2025). "In a case-control study of ovarian cancer, patients with BRCA1 or BRCA2 mutations showed higher response rates to platinum-based chemotherapy compared to patients without such mutations." (PMID 40557004, 2025). "The National Comprehensive Cancer Network (NCCN) guidelines recommend RRSO for ovarian cancer risk reduction by age 35-40 years for BRCA1 mutation carriers, and by age 40-45 years for BRCA2 variant carriers." (PMID 40862027, 2025). "Important germline mutations related to breast and ovarian cancer such as BRCA1 and BRCA2 (BRCA1/2) have been identified, and other high- and moderate-risk genes have been found to be associated with increased risk for these cancers." (PMID 40710012, 2025). "The most well‐known genetic factors of hereditary breast and ovarian cancers are the high penetrance pathogenic variants in the BRCA1 (HGNC:1100) and BRCA2 (HGNC:1101) genes." (PMID 39907309, 2025). "We compared the transcriptomic profiles of breast and ovarian cancers harboring mutations in BRCA1 and BRCA2 to identify differential transcriptomic patterns of expression." (PMID 40647506, 2025). "Both BRCA1 and BRCA2 alterations serve as a pathogenic basis for HBOC and are associated with increased susceptibility to breast or ovarian cancer." (PMID 40249378, 2025). "Given the chromosomal instability and heterozygous loss in BRCA2, a targeted therapy with the PARP-inhibitor olaparib was initiated 8 months after the first diagnosis of the ovarian carcinoma." (PMID 39820556, 2025). "BRCA1 and BRCA2 gene frequencies in breast and ovarian cancer patients in other East-Asian populations have been continuously researched on which had led to the discovery of potential founder mutations." (PMID 40531958, 2025). "Medically actionable variants were also identified in two other cancer-related genes, including BRCA2 and MSH6, which are associated with hereditary breast and/or ovarian cancer and Lynch syndrome, respectively." (PMID 40699671, 2025). "In the present article, we identified upregulated genes expressed in the surfaceome of breast and ovarian cancers with mutations in the BRCA1 and BRCA2 genes." (PMID 40647506, 2025).
ovarian carcinoma (continued). "For tubal/ovarian cancer, the average cumulative risk by the age of 80 is 44% [95%CI = 36–53] for BRCA1 and 17% [95%CI = 11–25] for BRCA2 GPV carriers, compared to a lifetime risk of 1.2% in the general population." (PMID 40427184, 2025). "In the case of hereditary ovarian cancers, they are associated with the carrier of mutations in the terminal BRCA1/BRCA2 genes." (PMID 40429755, 2025). "The most critical genetically determined risk factors for ovarian cancer (OvCa) are germline BRCA1 and BRCA2 mutations, which result in dysfunction of DNA repair mechanisms." (PMID 41008855, 2025). "A third observation in BRCA2-null ovarian cancer cells is that basal Tcf1/7 is highest in these cells." (PMID 39028933, 2024). "The ovarian cancer incidences for BRCA2 carriers were lower compared to BRCA1 carriers (incidences per 1000 person-years increased from 2 at age 60 to 11 at age 80)." (PMID 38333895, 2024). "The use of PARP inhibitors, particularly in BRCA1- and BRCA2-mutant ovarian cancers, has revolutionized the management of these patients and has been one of the most successful achievements in the last decade in the field." (PMID 39028933, 2024). "Above all, BRCA1 (breast cancer gene 1) and BRCA2 (breast cancer gene 2) are the most common contributors to breast/ovarian cancers." (PMID 38279352, 2024). "The cumulative risk (95% CI) of ovarian cancer to age 80 was 31% (27–36%) for BRCA1 carriers and 12% (10–15%) for BRCA2 carriers." (PMID 38333895, 2024). "Consistently, our findings on ovarian cancer reveal higher prevalences of BRCA1 and BRCA2 mutations in subtypes 1 and 3, which are associated with better survival and responses to treatments compared to subtype 2." (PMID 39199616, 2024). "In contrast to the activation of canonical Wnt signaling in ovarian cancer cells with functional BRCA1 and BRCA2, our results show that loss of BRCA1 leads to the activation of the noncanonical Wnt signaling pathway in response to Wnt3A." (PMID 39028933, 2024). "Increasing genetic referral and expanded testing resulted in higher estimated rates of risk-reducing surgery and lower incidence of breast and ovarian cancer in relatives of probands with a P/LP variant in BRCA1, BRCA2 or PALB2." (PMID 39766065, 2024). "Nevertheless, the confidence intervals for the ovarian cancer RR estimates for BRCA2 carriers are wide, larger studies are needed to improve the precision of these estimates." (PMID 38333895, 2024). "The ovarian cancer RR (95% floating-CI) was 3.3 (1.2–10.2) for BRCA2 carriers born in 1940–1959 compared to those who were born before 1940." (PMID 38333895, 2024). "The frequency of BRCA2 c.10234A > G observed in Chinese ovarian cancer patients was 1.64 times higher than that of in normal people." (PMID 38509102, 2024). "In this study, we have defined breast and ovarian cancer risk estimates for BRCA1 and BRCA2 PV carriers in Malaysia and Singapore." (PMID 38333895, 2024). "The risk of ovarian cancer in BRCA1 mutation carriers, which ranges from 39 to 46% by the age of 70, and for BRCA2 mutation carriers, ranging from 10 to 27% by the same age, underscores the impact of these genetic alterations on disease incidence." (PMID 38543119, 2024). "Vietri and coworkers described 2 families with DH PSV in BRCA1 and BRCA2 and concluded that earlier age at BC diagnosis (32 years) and ovarian cancer diagnosis (36 years) imply that the phenotype is more severely affected by the BRCA1 PSV." (PMID 39102164, 2024).
ovarian carcinoma (continued). "After BRCA1 and BRCA2, FANCJ is the third most common ovarian cancer susceptibility gene: nearly 0.9– 2.5% of all ovarian cancer patients carry a splice-site, stop, or frameshift mutation in the FANCJ gene." (PMID 38177925, 2024). "Germline BRCA1 and BRCA2 testing for clinically indicated breast and ovarian cancer patients has proven cost-effective worldwide and in Thailand16–18." (PMID 38355628, 2024). "BRCAPro is a Bayesian computer program or statistical model for calculating an individual’s probability of being a carrier of BRCA1/BRCA2 PGVs, based on the type of cancer and history of BC and/or ovarian cancer among relatives of the first and second degree." (PMID 38672070, 2024). "Breast and ovarian cancers are prevalent worldwide, with genetic factors such as BRCA1 and BRCA2 mutations playing a significant role." (PMID 38660159, 2024). "It is of much import halachically that the risk for ovarian cancer becomes significant after 35–40 for BRCA1 mutation carriers and 5–10 years later for BRCA2 mutation carriers." (PMID 38717180, 2024). "In 1994, through extensive research on families with a history of early-onset breast and/or ovarian cancer, the discovery of the connection between BRCA1 and BRCA2 genes and the development of cancer risk was made." (PMID 38397209, 2024). "The cumulative risks of developing ovarian cancer by the age of 70 differ among carriers of BRCA1 and BRCA2 mutations." (PMID 38391958, 2024). "The results also mirrored our general knowledge concerning the genetic background of hereditary breast and ovarian cancer, as variants in either one of the BRCA1 and BRCA2 genes proved to be the most common cause among our patients with 41.5%." (PMID 39148954, 2024). "A retrospective cohort study from 2015 showed an increase of ovarian cancer risk following HRT both for pV-carriers in the BRCA1 gene (OR 1.66; 95% CI 0.89–3.08; p < 0.001) and in the BRCA2 gene (OR 3.04; 95% CI 1.19–7.8; p < 0.001)." (PMID 39259360, 2024). "The purpose of this study was to evaluate RB1 expression and survival across ovarian carcinoma histotypes and how co-occurrence of BRCA1 or BRCA2 (BRCA) alterations and RB1 loss influences survival in tubo-ovarian high-grade serous carcinoma (HGSC)." (PMID 38837893, 2024). "In contrast, the unique response to Wnt signaling in BRCA2-null ovarian cancer cells can potentially enhance responsiveness to treatment and improve survival." (PMID 39028933, 2024). "The study included patients with advanced (FIGO stage III or IV) epithelial ovarian cancer and BRCA1 and/or BRCA2 mutations." (PMID 39590126, 2024). "BRCA1 and BRCA2 PVs confer increased risks of prostate, pancreatic, and ovarian cancers, while moderate-to-high risks of pancreatic (OR 4.21), prostate (OR 2.58), and gastric (OR 2.97) cancers were estimated for ATM-variant carriers." (PMID 38929805, 2024). "Ovarian cancers with BRCA1 alterations (germline and somatic mutations in 12% of cases, DNA hypermethylation in 11% of cases) and BRCA2 alterations (germline and somatic mutations in 11% of cases), are associated with homologous recombination deficiency (HRD)." (PMID 38952544, 2024). "The recommended ovarian cancer control guidelines include discussion of risk-reducing salpingo-oophorectomy (RRSO) at ages 35–40 for BRCA1 carriers and 40–45 years for BRCA2 carriers." (PMID 38333895, 2024). "Out of the seven patients who had both breast and ovarian cancer (metachronous), five had undergone genetic testing, with P/LP variant found in all five patients (four BRCA1 and 1 BRCA2)." (PMID 38439815, 2024).